MYC (MYC proto-oncogene, bHLH transcription factor)
Diseases named in the same sentence as MYC in open-access papers (continued):
Sharing a sentence is not in itself a finding about the gene and the disease.
glioma (continued). "In addition, miR-34a can indirectly regulate MYC expression through Wnt signaling pathway in glioma." (PMID 26335888, 2015). "Together, these studies delineate a comprehensive picture wherein MYC orchestrates multiple adaptive processes including metabolic reprogramming, DNA replication, and ER stress responses that converge to promote tumor growth, progression, and treatment resistance, particularly in aging gliomas." (PMID 40718795, 2025). "Notably, the MYC pathway is crucial for the onset of gliomas." (PMID 40469294, 2025). "However, in glioma stem cells, YTHDF2 promotes glioma stemness by stabilizing MYC and VEGF mRNA." (PMID 38637831, 2024). "The FTO/m6A/MYC/CEBPA signaling pathway may be related to TMZ resistance in glioma cells." (PMID 36437944, 2022). "Besides, MYC also exerts an important effect on the promotion of mitosis in glioma." (PMID 34446611, 2021). "Additionally, GSEA showed that MYC and E2F target genes were downregulated in miR-124-transduced cells, and these cells display expression dynamics comparable to that observed after miR-21 inhibition in glioma cells." (PMID 33333886, 2020). "However, there was little evidence to suggest that MYC was associated with chemosensitivity of glioma cells." (PMID 32916774, 2020). "Although MYC and CDK1 were prioritized based on their consistent upregulation and well-established roles in glioma biology, it is likely that EGR3 governs a wider transcriptional network influencing multiple aspects of tumor progression." (PMID 40649712, 2025). "Bioinformatics screening revealed that TRMT6 is highly expressed in high-grade gliomas and is involved in regulating the cell cycle and the PI3K-AKT, TGF-β, MTORC1, NOTCH, and MYC pathways to promote glioma proliferation." (PMID 40469294, 2025). "Conversely, MYC binds to the TMEM44‐AS1 SE, promoting its glioma‐specific transcriptional activation." (PMID 39690143, 2024). "During glioma progression, TMEM44‐AS1 binds directly to SerpinB3 and sequentially activates MYC and the EGR1/IL‐6 signalling pathway." (PMID 39690143, 2024). "R-2-hydroxyglutarate (R-2HG) has similar effects, which reduces MYC/CEBPA transcript stability and suppresses relevant pathways, with similar effects seen in glioma, suggesting R-2HG’s potential for targeting FTO/m6A/MYC/CEBPA signaling in FTO-high cancers." (PMID 39459530, 2024). "As previously demonstrated for gliomas in general, both the incidence of a PMN hit and the expression of MYC increased in parallel to the grade of the tumour in IDH-mutant astrocytomas." (PMID 38877600, 2024). "MYC dysregulation is pivotal in the onset and progression of IDH-mutant gliomas, mostly driven by copy-number alterations, regulatory element alterations, or epigenetic changes." (PMID 38877600, 2024). "This interaction creates a positive feedback loop involving TMEM44‐AS1 and MYC, highlighting the importance of the TMEM44‐AS1‐MYC axis in glioma progression." (PMID 39690143, 2024). "In this study, we report that MAD2L2 was upregulated in glioma and that high MAD2L2 expression promotes glioma proliferation, invasion, and maintenance of its stemness by regulating the oncogene c-MYC." (PMID 38017538, 2023).
glioma (continued). "Transcription factor PAX5 (Paired Box Gene 5) promotes gliomagenesis and cooperates with factors such as MYC, FOS, or JUN, which are highly expressed in gliomas." (PMID 36850002, 2023). "Bioinformatic analysis has shown that TRMT6 potentially influences glioma progression by being involved in cell cycle regulation, and the upregulation of PI3K-AKT, TGF-beta, mTORC1, NOTCH and MYC signaling pathways and other vital processes." (PMID 36012529, 2022). "The data showed that IPS reprogramming factors and pluripotency-related genes (POU5F1, SOX2, KLF4, MYC and NOTCH1) were detected in almost all histologic types and grades of gliomas." (PMID 36435765, 2022). "we performed the co-expression analysis and confirmed that CAPG2 positively correlates with the expressions of well-defined glioma stem cell marker genes, including Sox2, CD44, MYC and CCND1." (PMID 35898895, 2022). "While downregulation of TRIM47 lowered the expression levels of β-catenin, c-MYC, and cyclin D1, exogenous activation of Wnt/β-catenin signaling abolished the previous effects of TRIM47 knockdown observed in glioma cells." (PMID 36139694, 2022). "Mechanistically, studies have revealed that the JNK pathway, NOTCH pathway, RAS/MYC axis and Rb/E2F1 pathway participate in the development of H3.3K27M-positive gliomas." (PMID 36230759, 2022). "The overexpression of β-catenin in high-grade gliomas is a possible outcome of the aberrant activation of the canonical Wnt/β-catenin pathway, which in turn leads to the activation of CCND1 and MYC in gliomas." (PMID 36358663, 2022). "In this study, R-2HG was used to directly inhibiting FTO in AML and glioma cells, which resulted in increased methylation and decreased expression of c-MYC and CEBPA mRNAs, blocking proliferation, cell cycle, and inducing apoptosis in AML and glioma cells." (PMID 33461542, 2021). "We next repeated this process for each grade of glioma and found that these enhancers regulated a number of cancer-related genes, such as ARID1B 39, EGFR, MDM2 40, PRGFRA, and MYC." (PMID 33537074, 2021). "In glioma, PKM2 mediates phosphorylation of histone H3 on threonine 11, resulting in the transcriptional activation of c-MYC, cyclin D1 and tumour progression." (PMID 34847775, 2021). "Our study clarified the new mechanism by which LINC00470 acts as a ceRNA to sponge miR‐134, thereby regulating downstream molecules such as MYC and ABCC1 to maintain the malignant phenotype of glioma." (PMID 32916774, 2020). "We concluded that LINC00470 promoted the expression of MYC and ABCC1 by suppressing miR‐134, thus promoting glioma cell proliferation and invasion, and attenuating TMZ chemosensitivity." (PMID 32916774, 2020). "Although we identified the role of LINC00470 and miR‐134 in glioma and established the LINC00470/miR‐134/MYC/ABCC1 axis, certain limitations out of our study remain and should be improved upon in the future." (PMID 32916774, 2020). "We show that LN18 and U87 glioma polarise primary human microglia cultures towards the pro-tumorigenic, immunosuppressive phenotype (up-regulation of IL10, MYC) in vitro." (PMID 32390004, 2020). "GCM from control LN18 and U87 cells (shNeg) induced IL10 and MYC expression in human microglia, while knockdown of CSF2 in glioma cells reverted IL10 mRNA to the basal levels." (PMID 32390004, 2020). "Of course, a corollary of their observation should be that, in low grade, IDH1/2 mutant gliomas, the levels of FTO, kept low by R-2HG, result in an overall high level of m6A (or likely m6Am) RNA methylation, particularly relevant on MYC transcripts." (PMID 32316617, 2020). "We further explored the correlation between MYC/OCT4 and miR-9 transcript expression in glioma cells." (PMID 30795814, 2019).
glioma (continued). "In this study, we elucidate that MYC or OCT4 increases the expression of miR-9 by directly binding to its promoter region and thus regulates glioma tumorigenesis and angiogenesis through a miR-9 involved axis." (PMID 30795814, 2019). "For instance, TUG1 maintains stemness features of glioma stem cells via sponging miR-145 to promote SOX2 and MYC expression." (PMID 28983240, 2017). "Expression of MYCN correlated with that of SGO1/SGO2, except in lower-grade gliomas, and SGO1/SGO2 expression tended to be higher in some MYC-overexpressing cancers." (PMID 27539729, 2016). "This is the case of GATA3 in breast tumors, ZNF292 in low grade gliomas, ARID5B in uterine carcinomas, and MYC in diffuse B-cell lymphomas." (PMID 26792175, 2016). "The ODA14 tumour was selected after quantitative PCR screening of a series of gliomas for amplification of the EGFR,MET,MYC and PDGFRA genes, which are known to be recurrently amplified in these tumours." (PMID 25378339, 2014). "Furthermoe, the levels of several NF-κB target genes, TNF-α, IL-6, CCND1, MYC, BcL-XL and MMP-9, were upregulated in Bmi-1-overexpressing, but downregulated in Bmi-1-silenced glioma cells." (PMID 23383216, 2013). "To do so, we first transfected glioma cells with combinations of IDH1-WT and IDH1-R132H with MYC-FLAG or EGFP tags." (PMID 21326614, 2011). "All three high grade lines had highly complex genomic profiles and harboured amplifications and deletions at several known cancer genes dysregulated in paediatric glioma, including CCND1, MYC, CDK4, PIK3CA, CDKN2A/B, and RB1." (PMID 19365568, 2009). "PDGFRA signaling actively remodels the glioma microenvironment, contributing to vascular abnormalities (e.g., via the PDGFRA-Endocan-MYC axis), metabolic reprogramming that impairs T cell function, and immune cell polarization, all of which restrict anti-tumor immunity." (PMID 41847712, 2026). "Genomically, the tumor is H3 K27/G34 wild-type and shows no alterations in MYCN, MYC, or tyrosine kinase receptors, which are commonly seen in pediatric high-grade gliomas." (PMID 41323387, 2025). "Further, increasing MYC expression in human neural stem cells stimulates KAT5 activity and protein translation, as well as confers sensitivity to homoharringtonine, to similar levels to those found in GSCs and high-grade gliomas." (PMID 40346033, 2025). "Similarly, treatment with cyanidin was shown to suppress glioma stem cell (GSC) viability via downregulating β‐catenin and Wnt target genes such as MYC and TWIST1." (PMID 40589077, 2025). "MYC was identified as a key transcriptional regulator of ESURATAG, with strong correlations to aging and EMT signatures, indicating MYC-driven ER stress adaptation fuels aging-related glioma progression." (PMID 40718795, 2025). "ESURATAG-GS serves as a critical MYC-regulated adaptive mechanism that fuels aging-related tumor aggressiveness via ER stress-driven UPR in gliomas, presenting novel prognostic markers and therapeutic targets for elderly glioma patients." (PMID 40718795, 2025). "Furthermore, IHC staining on human glioma specimens confirmed a positive correlation between TGFBI and c-MYC level." (PMID 39346536, 2024). "Distal enhancer on 8q24 mediates MYC transcription through beta catenin/TCF4 signaling, and silencing of FAM84B markedly reduced the level of active beta catenin and the transcription activity of TCF/LEF in glioma." (PMID 38997648, 2024). "FERMT1 knockdown significantly suppressed of MYC, OCT4 and NANOG expression in U-251 MG and T98G cells, which coordinately supported the regulatory role of FERMT1 in self-renewal and stem cell-like properties in glioma." (PMID 38976072, 2024).
glioma (continued). "FTO overexpression enhances the stability of c-MYC mRNA through the m6A methylation-dependent mechanism, thereby improving MYC transcription, promoting the MYC feedback loop, and enhancing malignant characteristics of glioma cells." (PMID 38072944, 2023). "The evidence suggests that c-MYC mediates the tumor-promoting effects of the MAD2L2, and MAD2L2/ c-MYC may serve as a potential therapeutic target for glioma treatment." (PMID 38017538, 2023). "The m1A methyltransferase TRMT6 may contribute to glioma progression by modulating the cell cycle and affecting various pathways, including the PI3K-AKT, TGF-β, mTORC1, NOTCH, and MYC pathways." (PMID 37964279, 2023). "Primary CNS tumors with MYC alterations include but are not limited to oligodendroglioma, adult and pediatric gliomas regardless of IDH status, central neurocytoma, spinal ependymoma, medulloblastoma, AT/RT, pineoblastoma, and diffuse large B-cell lymphoma." (PMID 37173979, 2023). "Despite the implication of proto-oncogene family MYC in several metabolic processes, including nucleotide synthesis, lipogenesis, glucose transport, and glycolysis, its role in some gliomas, such as adult GBM, for which the MYC is rarely amplified, was not fully understood until recently." (PMID 35912242, 2022). "In addition, the inhibition of GSK3 activity results in c-MYC activation leading to the induction of Bax, Bim, DR4/DR5, and TRAIL expression and subsequent cytotoxicity in glioma models." (PMID 35402914, 2022). "In this pathway, MYC inhibits the expression level of MXI1 by affecting the expression of miR-155 and miR-23a, and MXI1 can also inhibit the expression level of MYC, thus forming a feedback loop to regulate glioma tumorigenesis and cell proliferation." (PMID 35688823, 2022). "In glioma, HELLS regulates the proliferation of stem cell-like glioblastoma stem cells by interacting with key oncogenic TFs E2F3 and MYC; targeted the inhibition of HELLS and prolonged survival in mice and improved the prognosis of patients with increased HELLS expression." (PMID 35774795, 2022). "Mechanistically, TRMT6 may be involved in glioma progression by regulating cell cycle, PI3K-AKT, TGF-beta, MTORC1, NOTCH, and MYC pathways." (PMID 34631793, 2021). "Particularly, MYC, CCND2, and ARID1B were regulated by more than six enhancers in gliomas." (PMID 33537074, 2021). "Likewise, c-Myc-dependent sensitivity to glutamine deprivation, termed glutamine addiction, has also been described in glioma SF188 cells and can be repressed by molecularly targeting MYC expression." (PMID 34503295, 2021). "Overall, these findings showed that TRMT6 might be involved in glioma progression by regulating cell cycle, PI3K-AKT, TGF-beta, MTORC1, NOTCH, and MYC pathways." (PMID 34631793, 2021). "Thus, we identified the LINC00470/miR‐134/MYC/ABCC1 axis and illuminated its biological role and mechanism in glioma." (PMID 32916774, 2020). "More importantly, we found that c-MYC could regulate expression of LPP-AS2, suggesting that LPP-AS2 is transcriptionally regulated by c-MYC, and functions as an oncogene in glioma via an miR-7-5p/EGFR/PI3K/AKT/c-MYC feedback loop." (PMID 32962742, 2020). "That is, LINC00470, miR‐134, MYC and ABCC1 can form a new regulatory axis in gliomas." (PMID 32916774, 2020). "Furthermore, we determined that LINC00470 indirectly regulates the expression of MYC by sponging miR‐134, thus regulating the malignant phenotype and TMZ sensitivity of glioma cells." (PMID 32916774, 2020). "Our study revealed a co‐expression relationship between MYC and ABCC1 and that the overexpression of MYC up‐regulated ABCC1, indicating that MYC may affect the drug resistance of glioma cells by regulating ABCC1." (PMID 32916774, 2020). "Our results provide a new understanding of the role and mechanism of the LINC00470/miR‐134/MYC/ABCC1 axis in glioma, which may contribute to the development of novel therapeutic targets and improve the chemosensitivity of glioma." (PMID 32916774, 2020).
glioma (continued). "Transcriptional regulation of miR-9 by MYC and OCT4 was determined in glioma cells." (PMID 30795814, 2019). "For example, recurrent translocations of PVT1-MYC or PVT1-NDRG1 were identified in a large study on medulloblastoma, the most malignant brain tumor in children, or genomic amplifications of MYC/PVT1 in pediatric gliomas." (PMID 31781490, 2019). "Importantly, USP28 promoted MYC expression, which was required for USP28-induced cell growth in human glioma." (PMID 29415985, 2018). "We further examined the expression of pri-let-7a-1, pri-let-7f-1, pri-let-7d and MYC in three human GBM cell lines from high-grade tumors (U-373 MG, U-87 MG, and U-251 MG), one low-grade glioma (SW-1088), and a malignant neuroectodermal tumor (PFSK-1) by Real-Time PCR assays." (PMID 27409345, 2016). "For instance, enhancer of zeste homolog 2 (EZH2), a histone methyltransferase involved in the upregulation of c-MYC, was shown to be highly involved the tumorigenesis of GBM and decreased the survival rates, therefore representing an important prognostic factor related to the grade of the glioma." (PMID 36425564, 2022). "In addition, high levels of MYC and PRMT5 correlate with glioma malignancy." (PMID 31694585, 2019). "let-7b has suspected tumor suppressor function in gliomas and low expression of the let-7 family members may be responsible for the poor prognosis of brain tumors patients through disturbed inhibition of KRAS, HMGA2 and MYC oncogenes." (PMID 31170943, 2019). "Additionally, a recent mouse model has demonstrated the potential of MYC to induce gliomagenesis in mature astrocytes, while a comparison of paired grade II and grade III gliomas has suggested a role of MYC in driving glioma progression." (PMID 28333115, 2017). "The genes downregulated by Sulfopin were also enriched for MYC-bound genes identified in several non-glioma cell lines, supporting a role for PIN1 in activation of the MYC pathway also in these glioma cells." (PMID 39093942, 2024). "First, primary and lined glioma cells were infected with or without ADV, and the expression of pluripotency factors c-MYC, SOX2, OCT4 and NANOG were determined by RT-qPCR and western blotting." (PMID 32843056, 2020). "While the mRNA levels of genes related to pluripotency (SOX2, KLF4, MYC and NOTCH1) were not obviously correlated with the clinical glioma grade or outcome, the mRNA level of POU5F1, which also plays a crucial role in PGC specification, was often linked to a higher glioma grade and poor outcome." (PMID 36435765, 2022).